LINC01801 (long independently transcribed non-coding RNA 1801)
Synonyms: LINC03049
Gene: Long non-coding RNA gene on chromosome 19 (34,788,527 to 34,860,747, reverse strand). Ensembl gene ENSG00000267767.
Diseases named in the same sentence as LINC01801 in open-access papers:
LINC01801 is named in the same sentence as 2 diseases in open-access papers, as found by Europe PMC text mining. Sharing a sentence is not in itself a finding about the gene and the disease.
LINC01801 shares sentences with these, for which no sentence is quoted: prostate tumor (1 paper); Sepsis (1).